LGALS3 (galectin 3)
Diseases named in the same sentence as LGALS3 in open-access papers (continued):
Sharing a sentence is not in itself a finding about the gene and the disease.
Huntington disease (18 papers, 2019 to 2025). Huntington disease (HD) is a rare neurodegenerative disorder of the central nervous system characterized by unwanted choreatic movements, behavioral and psychiatric disturbances and dementia. "It appears that Galectin-3 also plays a role in brain inflammation associated with Huntington’s disease (HD)." (PMID 32455781, 2020). "In accordance, a recent report demonstrated that Galectin-3 KO in the brains of Huntington’s disease model R6/2 mice significantly upregulated expression of IL-10 in striatal lysates." (PMID 36076283, 2022). "A Chinese study showed that the levels of galectin-3 in the brains of patients with Huntington's disease (HD) and mice were higher than those of the control cohort and were related to the severity of the disease." (PMID 34900086, 2021). "The authors show that Galectin-3 is up–regulated in brain tissues from patients and a mouse model of Huntington’s disease (HD) and correlates with disease severity." (PMID 31375685, 2019). "In addition, galectin-3 increases interleukin (IL)-1β expression in microglia from a murine model of Huntington’s disease." (PMID 36008956, 2022). "Galectin-3 is also increased in the serum of patients with Huntington's disease." (PMID 34720894, 2021). "Similarly, brain levels of galectin-3 are higher in patients and mice with Huntington disease and selective galectin-3 knockdown suppressed inflammation, reduced mutant huntingtin aggregation, and improved motor dysfunction." (PMID 32709045, 2020). "Also, it was shown that the expression of galectin-3 is upregulated before motor impairment and that its expression levels persisted in activated microglia throughout disease progression in a murine model of Huntington’s disease." (PMID 37491623, 2023). "Galectin-3 controls the severity of inflammation and induces the activation of NLRP3 inflammasome-dependent pathways in Huntington's disease and spinal cord injuries." (PMID 34720894, 2021).
metastatic disease (18 papers, 2010 to 2025). "In metastatic tumors TDO2 was expressed four-fold higher than in non-metastatic tumors, but LGALS3 was two-fold lower." (PMID 36430322, 2022). "This suggests a greater therapeutic efficacy of inhibition of LGALS3 in the early stages of GC in relation to metastatic tumors, if any." (PMID 36430322, 2022). "The expression of TDO2 four-fold higher in metastatic tumors than in non-metastatic tumors, but LGALS3 was two-fold lower." (PMID 36430322, 2022). "Galectin-3 levels have been found to be significantly decreased in primary carcinomas and metastatic disease compared to normal and premalignant prostatic tissue." (PMID 25667921, 2015). "In contrast, galectin-3 expression was significantly decreased in primary carcinoma and metastatic disease compared with normal and premalignant tissue." (PMID 23658855, 2010). "Galectin-3 concentrations in sera from the patients with a metastatic disease were significantly higher than in sera from the patients with localized tumors." (PMID 23658855, 2010). "The Galectin-3 levels in serum or plasma measured in our cohorts were comparable to Galectin-3 serum and plasma levels in healthy subjects measured by us and others, indicating that Galectin-3 levels are specifically increased at the primary and metastatic tumor sites." (PMID 39759523, 2024). "Interestingly, higher concentrations of galectin-3 were detected in metastatic tumors than in primary tumors." (PMID 36873388, 2023). "Circulating galectin-3 in patients with metastatic tumor were significantly elevated." (PMID 36386163, 2022). "Moreover, higher galectin-3 expression has been shown in patients with metastatic disease than in patients with localized tumors." (PMID 23265237, 2012). "In metastatic tumors, LGALS3 was expressed two-fold lower than in non-metastatic one." (PMID 36430322, 2022). "In metastatic tumors, TDO2 expression was higher (p = 0.024) and LGALS3 expression was lower (p = 0.031) relative to tumors without metastases." (PMID 36430322, 2022).
osteosarcoma (18 papers, 2006 to 2025). A usually aggressive malignant bone-forming mesenchymal neoplasm, predominantly affecting adolescents and young adults. "Khanna and colleagues (2001) have shown that galectin-3 accumulates in more metastatic osteosarcoma cells, thus providing an association between galectin-3 expression and a more invasive phenotype." (PMID 22216245, 2011). "Since galectin-3 (LGALS3) is expressed in pituitary tumors, it is possible that its expression is also elevated in osteosarcomas." (PMID 37370857, 2023). "More recently, a novel interaction was identified between FGFR1 and galectin-1 (LGALS1)/galectin-3 (LGALS3) in osteosarcoma cells ectopically expressing FGFR1." (PMID 34068954, 2021). "Accumulation of galectin-3 in transformed highly migratory fibroblasts and invasive osteosarcomas prompted us to investigate its possible role as a modulator of integrin function in tumor cells of mesenchymal origin." (PMID 22216245, 2011). "Significantly higher levels of galectin-3 were also found in patients with osteosarcoma, and the authors assume that serum galectin-3 could serve as a useful biomarker for the evaluation of osteosarcoma progression." (PMID 35410028, 2022). "Interestingly, it was demonstrated that galectin-3–mediated β-catenin expression through FAK activation promotes osteosarcoma cell migration, and chemoresistance." (PMID 32373510, 2020). "In pituitary tumours, RUNX2 upregulates the anoikis suppressor galectin-3 (LGALS3), which may also facilitate osteosarcoma metastasis." (PMID 21197465, 2011). "Similar to our data, downregulation of galectin-3 by siRNA in ovarian clear cell carcinoma and osteosarcoma (to approximately 33%) did not affect proliferation and apoptosis of cancer cells; however, in combination with cisplatin, it increased the extent of apoptosis and inhibited proliferation." (PMID 30585294, 2019).
pneumonia (18 papers, 2016 to 2024). An acute, acute and chronic, or chronic inflammation focally or diffusely affecting the lung parenchyma, caused by an infection in one or both of the lungs (by bacteria, viruses, fungi, or mycoplasma.). "Serum galectin-3 enabled the diagnosis of pneumonia with moderate diagnostic accuracy and the need for ICU treatment with high diagnostic accuracy." (PMID 34439802, 2021). "In multiple logistic regression, galectin-3 was significantly associated with pneumonia and ICU treatment independently of age and Charlson comorbidity index." (PMID 34439802, 2021). "Furthermore, Galectin-3 showed direct bacteriostatic properties against Streptococcus pneumonia in vitro, while recombinant Galectin-3 decreased severity of pneumonia in Galectin-3 deficient mice." (PMID 32455781, 2020). "More specifically, in pneumonia diagnosis, it has already been suggested that galectin-3 can trigger influenza-induced pulmonary inflammation through inflammasome activation." (PMID 37958814, 2023). "The results showed that Galectin-3 level was higher in patients with typical pneumonia findings on thorax CT." (PMID 36225452, 2022). "Serum galectin-3 was significantly increased in patients who developed pneumonia, particularly those who required ICU admission." (PMID 34439802, 2021). "Galectin-3 has been implicated in the regulation of suppressor of cytokine signaling 1 (SOCS1) and retinoic acid-inducible gene I (RIG-I) expression during influenza and Streptococcus pneumoniae co-infection." (PMID 37298569, 2023). "There are very few studies examining Galectin-3 levels in pneumonia cases." (PMID 36225452, 2022). "In patients with pneumonia, an almost twice higher serum galectin-3 concentrations were found compared with those, in whom no pneumonia developed (13.30 (8.93–17.38) ng/mL vs. 8.55 (6.73–10.98) ng/mL, respectively)." (PMID 35053194, 2021).
Hepatic steatosis (17 papers, 2012 to 2025). Steatosis is a term used to denote lipid accumulation within hepatocytes. "Hepatic steatosis, inflammation, and fibrosis (liver lipids, galectin-3, and collagen 1a1 [Col1a1], respectively), as well as plasma alanine transaminase (ALT) and aspartate transaminase (AST) levels, were assessed." (PMID 38662778, 2024). "Lastly, Galectin-3 is thought to promote hepatic inflammation in fatty liver disease via TLR-4-mediated NLRP3 inflammasome activation." (PMID 39635525, 2024). "Mice fed with the OYC-NASH2 diet for 3 weeks showed severe hepatic steatosis and inflammatory cell infiltration, and the expression of its related genes, such as Tnf, Ccl2, and Lgals3, was significantly increased at 3 weeks." (PMID 37509405, 2023). "LGALS3, SLC51B and SPP1 expression were in close association with the outcome of hepatic steatosis in both experimental approaches." (PMID 35046474, 2022). "The scores of hepatic steatosis (higher in Lgals3+/+ mice), portal inflammation and hepatitis (both higher in Lgals3−/− mice) indicated that liver injuries were aggravated in the absence of Gal-3." (PMID 31601823, 2019). "Initial in vivo studies demonstrated that the absence of the gene encoding for Gal-3, namely Lgals3, led to hepatic steatosis in mice." (PMID 40608687, 2025). "In the lobular zone, hepatic steatosis was predominant in the Lgals3+/+ mice whereas atypical cells (such as plasma cells and megakaryocytes) were frequently observed in dilated sinusoids in the liver of Lgals3−/− mice." (PMID 31601823, 2019). "Lgals3 also has been shown to regulate adipose tissue development and function, and may be an important molecule mediating how diet influences hepatic steatosis." (PMID 29716523, 2018). "Since we previously reported that synbiotic supplementation protected against hepatic steatosis and markers of oxidative stress, we analyzed liver sections in mice for the protein expression of receptors for AGE (RAGE) and galectin-3 by immunostaining and immunoblotting." (PMID 32023885, 2020). "GAN diet consistently drove a liver phenotype characterised by increased liver steatosis and inflammation, evident from histopathological scores (NAS, steatosis score, lobular inflammation score) and supported by quantitative image analysis (steatosis% % area, Galectin-3)." (PMID 40604130, 2025). "While down-regulation of DGAT1 in spheroids following LGALS3 silencing could have protective effects in condition of hepatic steatosis, changes in CPT1A and PPARA mRNA levels, might be a consequence of the lipid content reduction or represent an independent effect exerted by Gal-3." (PMID 40608687, 2025). "However, its role in fatty liver disease has not been as extensively investigated as galectin-3, which was not identified in our proteomic analysis, warranting further investigation." (PMID 35406736, 2022).
kidney damage (17 papers, 2011 to 2025). "Apelin, a regulator of insulin sensitivity, has demonstrated protective effects in diabetic retinopathy, while galectin-3 has been identified as a key factor in fibrosis and inflammatory responses, particularly in nephropathy and neuropathy." (PMID 40137149, 2025). "Similar results were observed regarding the protein expression of Galectin-3 (Gal-3), a well-known lectin that is highly involved in inflammatory cell adhesion during kidney damage." (PMID 39707203, 2024). "Our data indicates that MCP is protective in experimental nephropathy with modulation of early proliferation and later galectin-3 expression, apoptosis and fibrosis." (PMID 21494626, 2011). "Therefore, as part of this process is mediated by extracellular actions of galectin-3, we propose that MCP effects on inflammation in FA-nephropathy may in part be mediated by galectin-3." (PMID 21494626, 2011). "According to our observations, galectin-3 inversely correlates with GFR, indicating a relationship with kidney damage." (PMID 35742776, 2022).
lymph node metastasis (17 papers, 2011 to 2025). "The expressions of ezrin and galectin-3, histological grade, depth of stromal invasion, and lymph node metastasis are risk factors affecting the survival rate of patients with cervical cancer." (PMID 28355349, 2017). "Additionally, galectin-3 IHC expression is decreased in SCLC when compared to NSCLC, and studies have demonstrated that higher serum and tumor levels of galectin-3 in NSCLC are associated with lymph node metastasis and tumor recurrence." (PMID 38539500, 2024). "The expression of galectin-3 and -9 was found to be significantly elevated in lymph node metastases (p = 0.044 and p = 0.011)." (PMID 37238197, 2023). "On the other hand, lower expression of the CSC-associated genes ALDH1A3, LGALS3 and MYH9 and the pluripotency gene POU5F1 assessed by fingerprint values, were instead associated with the presence of lymph node metastases (LN Met)." (PMID 38124067, 2023). "The concomitant presence of circulating circRNA-UMAD1 and Galectin-3 is considered a “co-biomarker” for predicting TC lymph node metastasis." (PMID 36230649, 2022). "In our studies, higher serum galectin 3 levels were observed in patients with lymph node metastases." (PMID 32859099, 2020). "The expressions of ezrin and galectin-3 were both related with histological grade, deep myometrial invasion and lymph node metastasis (all P<0.05)." (PMID 28355349, 2017). "Spearman correlation regression analysis revealed a linear relationship between galectin-3 expression and histological grade, lymph node metastasis, and TNC (r = 0.297, 0.371, and 0.403, respectively, P = 0.011, 0.001, and 0.000, respectively)." (PMID 25254965, 2014). "We observed, that galectin-3 expression was higher in patients with lymph node metastases (tendency in Chi2 Yatesa test and statistical significance in Chi2 test)." (PMID 22024187, 2011). "In patients with lymph node metastases galectin-3 expression was revealed in 13 from 25 cases (52%), and without lymph node metastasis in 5 from 22 (22.7%)." (PMID 22024187, 2011). "This investigation suggests that galectin-3 may be involved in the pathogenesis of endometrial carcinomas and lymph node metastasis." (PMID 36578551, 2022). "The serum levels of Galectin-3 with lymph node metastasis were significantly higher than those of patients without lymph node metastasis (P < 0.01), and N2 lymph node metastasis had higher levels of serum Galectin-3 than those of N1 lymph node metastasis (P < 0.01)." (PMID 32429635, 2020). "Previous researches indicated that increased expression of galectin-3 often predicted unfavorable outcomes and the level of galectin-3 was positively correlated with invasion of depth, vessel invasion, lymph node metastasis, distant metastasis, and TNM stages of various cancers." (PMID 30410421, 2018). "Galectin-1 but not galectin-3 was associated with lymph node metastasis." (PMID 26448934, 2015). "Our study showed the serum levels of Galectin-3 are highly expressed in NSCLC patients and are significantly related to lymph node metastasis." (PMID 32429635, 2020). "The percentage of the cases with lymph node metastasis negative for galectin-3 expression (64%) was increased almost four-fold compared with cases without lymph node metastasis (18%)." (PMID 36578551, 2022). "However, galectin-3 or 90K/Mac-2BP levels were not correlated with lymph node metastasis (data not shown)." (PMID 26448934, 2015).
multiple sclerosis (17 papers, 2017 to 2025). A progressive autoimmune disorder affecting the central nervous system resulting in demyelination. "In multiple sclerosis (MS), galectin-3 expression is associated with demyelination and interacts with TREM2 to regulate inflammatory events." (PMID 40429840, 2025). "In viral-induced multiple sclerosis models, galectin-3 is essential for the neurogenic niche response in the SVZ." (PMID 40429840, 2025). "Galectin-3 also inhibits cell emigration from the SVZ in the cuprizone-induced multiple sclerosis model." (PMID 40429840, 2025). "In the case of mice with experimental autoimmune encephalomyelitis (EAE), a model of multiple sclerosis, a reduction in disease severity is presented when galectin-3 expression is suppressed." (PMID 36008956, 2022). "Galectin-3 (MAC-2) in microglia dynamically adjusts the state of actin/myosin-based contractions to lead to the retraction of filopodia/lamellipodia to damage myelin surrounding the central nervous system axons in multiple sclerosis." (PMID 37691828, 2023).
neuroblastoma (17 papers, 2012 to 2025). Neuroblastoma (NB) is the most common solid, extracranial childhood tumor. "To further examine the mitophagy function of Galectin-3 in neuronal mitophagy, we performed mitophagy flux assays in neuroblastoma cell line SH-SY5Y, which expresses endogenous levels of Parkin." (PMID 41194217, 2025). "Galectin-3 is broadly expressed in human neuroblastoma cell lines and tumors and is repressed by MYCN to induce the apoptosis-sensitive phenotype." (PMID 23152863, 2012). "Despite its reduced levels, Galectin-3 can still exert residual antiapoptotic effects in MYCN amplified neuroblastoma cells, possibly due to its specific subcellular localization." (PMID 23152863, 2012).